LEP (leptin)
Diseases named in the same sentence as LEP in open-access papers (continued):
Sharing a sentence is not in itself a finding about the gene and the disease.
Obesity (continued). "Treatment of human adipocytes with HCA-SX resulted in a significant down-regulation of 348 and induction of 366 fat- and obesity-related genes such as hormone sensitive lipase, peroxisome proliferator-activated receptors gamma (PPARγ), coactivator 1α, Leptin, and hypoxia-inducible factor-1 genes." (PMID 26912252, 2016). "For example, obesity may affect brain structure, leptin and insulin dysregulation, oxidative stress, cerebrovascular function, blood-brain barrier, and inflammation." (PMID 26881095, 2016). "Although rare mutations in the leptin (LEP)gene are well known to cause leptin deficiency and severe obesity, no common lociregulating circulating leptin levels have been uncovered." (PMID 26833098, 2016). "Leptin has been proposed as another mediator of the effects of obesity on brain structure." (PMID 27089992, 2016). "Mutations in the gene encoding leptin (LEP) typically lead to an absence of circulating leptin and to extreme obesity." (PMID 27928443, 2016). "Since plasma homocysteine levels increase with obesity, homocysteine-induced ER stress may also play a role in the development of leptin resistance." (PMID 27375555, 2016). "To determine whether chemical inhibition of EEF1A1 activity could improve hepatic lipotoxicity in a mouse model of obesity and metabolic syndrome, we used 5‐week‐old male C57BL/6J (lean control) and leptin‐deficient ob/ob mice." (PMID 27613825, 2016). "Thus, in obesity, plasma levels of leptin, anorexigenic adipose tissue-derived hormone, are elevated." (PMID 26862530, 2016). "Circulating leptin is strongly associated with both subcutaneous and visceral fat, and different studies have hypothesized that obesity might induce a state of leptin resistance." (PMID 27973438, 2016). "Data on the presence of leptin in infant formula are still controversial, however more investigations are needed to detect if hormones present in breast milk have a beneficial effect on obesity later in life." (PMID 27338468, 2016). "This suggests that leptin itself (and hence the obesity state) may modulate gut microbiota independently of the diet." (PMID 27043550, 2016). "Current data suggest that leptin signaling could be an essential link between obesity and cancer incidence and development." (PMID 27472371, 2016). "Leptin-deficient (ob/ob) mice develop obesity, hyperinsulinemia and hyperglycemia with the absence of hypertension and dyslipidemia." (PMID 27708685, 2016). "In contrast to genetic leptin or leptin receptor loss-of-function, which are extremely rare, heterozygous mutations in the melanocortin-4-receptor (MC4R) are the most common monogenic cause of obesity, accounting for around 6% of severe, early-onset obesity." (PMID 27899914, 2016). "Some of these molecules secreted by adipocytes are involved in the regulation of body weight (leptin, adiponectin), in the local inflammation generated in obesity (TNF-α, IL-6, and IL-1β), in vascular function (Ang II and PAI-1), or in breeding (estrogens, among others)." (PMID 27766104, 2016). "In addition to exercise, leptin replacement therapy, inhaled insulin therapy, and caloric restriction have also been proposed to improve obesity." (PMID 26881095, 2016). "Therefore, though leptin is now thought to be unsuccessful for the treatment of obesity, understanding the mechanisms of the development of “leptin resistance” has become a hot topic for research." (PMID 27746736, 2016). "In models of diabetes and obesity, where circulating glucose levels are elevated, we consistently observed feminization of liver STAT5b function, and feminization was at least partially reversed by leptin or resveratrol treatment." (PMID 26959237, 2016). "The drivers of the profound changes in lymphocytes and monocytes in the circulation and lung remain unknown, although leptin, which is increased in diet-induced obesity, is a known driver of lymphopoiesis and myelopoiesis." (PMID 26956558, 2016).
Obesity (continued). "It has previously been reported for both humans and rodents that obesity is associated with leptin resistance and that obese individuals have elevated leptin levels without any down-regulation of food intake." (PMID 26839578, 2016). "Hyperleptinemia is a characteristic manifestation of obesity in humans and rodents that develops with resistance to the action of leptin because the elevated circulating levels of this adipokine can no longer effectively perform its regulatory anorectic function." (PMID 27099927, 2016). "Furthermore, serum resistin and leptin have specific roles in the regulation of adipose tissue macrophages in patients with modest obesity or early metabolic dysfunction." (PMID 27101398, 2016). "Leptin is an anti-obesity hormone which plays a role in satiety regulation." (PMID 27739518, 2016). "Finally, the observed correlation with patients’ BMI further adds to previous reports of BAFF acting as an adipokine in obesity related severe asthma, along with leptin and adiponectin." (PMID 27513955, 2016). "Substantial research has shown that obesity affects our cognition and motor behaviors through different mechanisms, possibly through altering brain structure, leptin/insulin regulation, oxidative stress, cerebrovascular function, blood-brain barrier, and inflammation." (PMID 26881095, 2016). "Contrasting associations of serum leptin and CRP with cancer mortality may indicate sex‐specific biological or environmental pathways linking obesity and cancer in men and women which warrant mechanistic investigations." (PMID 26632325, 2016). "Obesity is a worldwide threat to public health in modern society, which may result from leptin resistance and disorder of thermogenesis." (PMID 27444146, 2016). "In the present work, we provide evidence that loss of PUMA influences circulating leptin levels and food intake but has no impact on glucose homeostasis in diet-induced obesity." (PMID 27033313, 2016). "It is well known that congenital leptin deficiency, due to mutations in leptin gene or leptin receptor gene, cause early-onset obesity and absence of pubertal development." (PMID 27746590, 2016). "Elevations of leptin and insulin contribute to obesity in rodent models." (PMID 27028862, 2016). "The general so-called leptin hypothesis of depression states that leptin insufficiency and leptin resistance both may contribute to the vulnerability for depression, and that leptin thus may represent the biological link between obesity and mood disorders." (PMID 28030575, 2016). "In obesity, leptin is assumed to drive sympathetic activity and to contribute to hypertension." (PMID 27147943, 2016). "Circulating leptin levels correlate with body fat mass, and are high in obesity." (PMID 26849804, 2016). "Hyperleptinemia and subsequent leptin resistance are associated with T2DM and obesity." (PMID 26432692, 2016). "Therefore, the amelioration of leptin resistance has recently been attracting interest as a treatment for obesity." (PMID 27375555, 2016). "Leptin, a 16 KDa protein hormone is a novel and very promising molecule of research that may act as a mediator between obesity and CVD." (PMID 25762868, 2015). "Unlike adiponectin, plasma leptin levels are increased in obesity and type 2 diabetes, reflecting a state of leptin resistance; and are independently associated with hypoadiponectinemia, insulin resistance, dyslipidemia, inflammatory markers, and CVD." (PMID 26030149, 2015). "Aiming to explore a potential link between irisin and obesity in human breast malignancy, we investigated potential correlations of irisin levels with body mass index (BMI) and with levels of the adipokines leptin, adiponectin and resistin in breast cancer patients." (PMID 26560078, 2015). "Leptin is a peptide hormone which is released by adipocytes and could inhibit obesity by stimulating satiety centers in brain (DePaoli, 2014 ▶)." (PMID 26693410, 2015).
Obesity (continued). "This metabolically-healthy obese population has a unique obesity phenotype and metabolism, and LEP and ADIPOQ DNA methylation profiles might be distinct in these participants." (PMID 25929254, 2015). "One explanation for these discrepancies and divergent data existing literature about obesity and βA system may be related to leptin levels, type of diet, animal model utilized and catecholamine levels." (PMID 26390297, 2015). "Among obesity-related factors that are known to impact breast cancer development and progression, the adipose-derived adipokine leptin, whose synthesis and plasma levels increase proportionally to total adipose tissue mass 6,7 has been extensively examined in this regard." (PMID 25721149, 2015). "It is thus tempting to speculate on whether the LEP epigenetic profile we are reporting in blood was established in utero and might have been involved in the development of obesity in the patients of the current study." (PMID 25929254, 2015). "It has been suggested that sleep restriction may lead to obesity via changes in the appetite regulating hormones leptin and ghrelin." (PMID 26448340, 2015). "Obesity is very common in type 2 diabetes where the adipocytes cells secret a number of biological proteins (leptin, TNF-alpha, resistin, and adiponectin) that modulate insulin secretion or action and may contribute to insulin resistance." (PMID 26273663, 2015). "Besides its function in regulation of appetite and metabolic balance and its role as an anti-obesity target and counterpart of leptin, it can also modulate leukocyte function." (PMID 25844479, 2015). "The mechanisms of leptin-stimulated cPLA2-α expression may be a link between obesity and lung inflammation-related pathologies, suggesting novel strategies for treatment." (PMID 26593914, 2015). "Brain transcriptome analyses in obese mice identified several obesity-related pathways (e.g. leptin, somatostatin, and nemo-like kinase signaling), as well as genes involved in feeding and appetite (e.g. Pmch, Neurotensin) and in metabolism (e.g. Bmp4, Bmp7, Ptger1, Cox7a1)." (PMID 25629159, 2015). "It is also possible that age of participants is crucial in analyses of the risks related to leptin since at higher age obesity is not strongly linked with morbidity and mortality." (PMID 25994184, 2015). "Our data, however, confirmed that BMI alone may be a strong predictor of clinical manifestations of obesity as a strong and significant correlation exists between leptin and BMI in obese diabetic population." (PMID 25897417, 2015). "Obesity also leads to increased levels of leptin creating a proinflammatory state which may affect lymphocytes number, function and the activation of immune cells." (PMID 25306890, 2015). "Thus, the concept of leptin resistance has emerged to explain the paradoxical elevated leptin levels in obesity." (PMID 26581745, 2015). "Elevated plasma leptin levels are observed in obesity and insulin resistance." (PMID 26368559, 2015). "Leptin is a hormone that was discovered in 1994, the product of research that has brought significant advances in the understanding of cardiovascular diseases (CVDs), obesity, and the metabolic syndrome." (PMID 25573199, 2015). "Impaired insulin signaling pathway may therefore, as with leptin, contribute to the development of neuropsychiatric symptoms in the context of obesity by interacting with brain cytokines." (PMID 26190966, 2015). "We suggest that leptin could be a surrogate marker of severity or chronicity of humoral immunity in RA in the presence of obesity." (PMID 26589684, 2015). "SM releases both adiponectin and leptin, and altered levels are indicators for obesity." (PMID 26690877, 2015). "This prominent rise in serum leptin levels suggest that metabolic parameters other than obesity might influence leptin secretion during pathological conditions thereby resulting in leptin resistance." (PMID 25762868, 2015).
Obesity (continued). "Many studies suggest an important participation of leptin in obesity-related hypertension." (PMID 25793389, 2015). "Linear regression demonstrated a positive correlation between leptin and obesity." (PMID 26770217, 2015). "Nonetheless, as both resistin and leptin are elevated in obesity, and they each have sympatho-excitatory actions on renal and lumbar sympathetic nerve activity, it is quite possible that the effects on those outputs is exacerbated when leptin and resistin are present together." (PMID 26617526, 2015). "In conclusion, present findings suggest that serum leptin may contribute to GFR decline independently of obesity and diabetes mellitus." (PMID 25710704, 2015). "We assume that this signaling pathway may be partly responsible for the relation between obesity–leptin-induced mitochondrial dysfunction and colon cancer." (PMID 26472027, 2015). "Henceforth, the objective of this study was to determine whether LEP and ADIPOQ DNA methylation levels in subcutaneous (SAT) and visceral (VAT) adipose tissues were associated with obesity and obesity-related complications severely obese men and women." (PMID 25929254, 2015). "The elevated baseline leptin levels, combined with an improved cellular immune system and additional increases of leptin in sepsis induced by both obesity and ghrelin treatment, might tip the ghrelin—leptin balance towards leptin." (PMID 25844479, 2015). "The anti-obesity and hypolipidemic effects of AFE + VME were associated with the up-regulation of the mRNA expression of PPAR-γ, UCP-2, and adiponectin and the down-regulation of leptin in high-fat-diet-induced obese mice." (PMID 26474757, 2015). "Also leptin, a hormone that is elevated in obesity, has been suggested to reduce aspirin efficacy through prothrombotic effects." (PMID 25993271, 2015). "Serum leptin is believed to play a role in obesity but, although leptin levels were strongly associated with HOMA-IR and weight status at baseline, in the present study, significant decrease in leptin levels were noted only in obese children at one year follow-up." (PMID 26581745, 2015). "Hence, further studies need to be done on leptin and specifically leptin resistance, in order to better understand leptin's function in obesity and promotion of cardiovascular diseases." (PMID 26064110, 2015). "Further studies are needed to determine whether leptin signaling plays a role in skewing fetal hematopoiesis under obesity and HFD, though its roles in lymphopoiesis, erythropoiesis, and myelocytic progenitor proliferation have been demonstrated in adults." (PMID 25685687, 2015). "Adipokines such as adiponectin as well as leptin have been demonstrated in the obesity-associated disorders, nonalcohol fatty liver disease (NAFLD) and hepatocellular carcinoma (HCC)." (PMID 25814788, 2015). "In this sense, we postulate that obesity could enrich the tumor microenvironment with cytokines or adipokines (e.g., leptin) that negatively influence cancer cell behavior." (PMID 26053184, 2015). "Survey of leptin in acute lymphoblastic leukemia (ALL) survivors could be helpful in controlling obesity." (PMID 26705449, 2015). "It has been hypothesized that leptin resistance in obesity could promote SM atrophy while the recovery of its function could reverse the loss of muscle mass." (PMID 26690877, 2015). "The inflammatory response of the hypothalamus to HFD-induced obesity can lead to decreased leptin and/or insulin sensitivity, which not only results in negative consequences in the regulation of food intake and energy balance, but also leads to secondary complications, such as type 2 diabetes." (PMID 25859240, 2015). "Taken together this suggests that high levels or disrupted blood rhythms of glucocorticoids may contribute to the leptin resistance observed in obesity." (PMID 26000016, 2015).
Obesity (continued). "Therefore, hypothalamic inflammation, specifically microglial activation and induction of NF-κB signaling, is involved in age-dependent and diet-induced obesity, which are accompanied by central leptin/insulin resistance." (PMID 26236282, 2015). "On the other hand, the low level of leptin in mice fed with the carbohydrate-rich diet could make these animals prone to obesity." (PMID 26634209, 2015). "We now describe two siblings, a 9-year-old girl and a 6-year-old boy with severe early-onset obesity and hyperphagia, both homozygous for a c.309C>A substitution in the leptin gene leading to a p.N103K amino acid exchange in the protein and detectable circulating levels of leptin." (PMID 26186301, 2015). "Indeed, microglia and astrocytes participate in the hypothalamic inflammatory response to high fat diet (HFD)-induced obesity, with this process contributing to inflammatory-related insulin and leptin resistance." (PMID 25859240, 2015). "Hence, under conditions of hypertension and obesity, leptin concentrations are augmented, leading to an increase in ROS production and oxidative stress, which in turn lead to dysfunction and vascular remodeling through oxidative damage." (PMID 26064110, 2015). "In terms of a potential causal role of leptin as a driver of breast carcinogenesis, preclinical data show that leptin regulates JAK2/STAT3 and inflammatory cytokine related signaling, which is altered by obesity and reregulated via weight loss." (PMID 26132992, 2015). "The absence of leptin expression, as a result of a mutation in the ob gene, induces severe obesity in mice, concomitant with multiple hormonal and metabolic alterations." (PMID 25946034, 2015). "In clinical settings, plasma leptin concentrations have found to be strongly and positively correlated to adiposity, suggesting that high leptin levels lose their ability to restrain feeding and fat accumulation in obesity." (PMID 26338087, 2015). "Key words:Periodontitis, obesity, inflammation, adiponectin, leptin." (PMID 26330934, 2015). "Therefore, it is reasonable to postulate that the effects of bilirubin on obesity are a consequence of altered lipid synthesis, reduction of leptin levels, and decreased TNF-α production." (PMID 26017184, 2015). "Although the mechanisms for obesity-induced oxidative stress remain unclear, leptin, an adipocyte-derived hormone, has been considered as an important contributor." (PMID 26435910, 2015). "Obesity-induced leptin plays a crucial role in NASH progression via enhanced response to endotoxin." (PMID 25658689, 2015). "Since hepcidin is induced by IL-6 and STAT3, it may also be induced by leptin, and if so, a higher body mass index and obesity could lead to elevated production of hepcidin." (PMID 25918733, 2015). "Obesity is shown to have a state of leptin resistance where there is hyperleptinemia." (PMID 25658689, 2015). "Likewise, other reports have described a role for obesity and leptin in regulating circulating NK cells, but authors have identified their NK cell population by other ways than the presence or absence of the CD56 marker." (PMID 26569331, 2015). "Leptin levels correlate with the levels of estrogen in premenopausal women; however, this correlation between leptin and estrogen often disappears in postmenopausal women and could help explain a rise in obesity in the postmenopausal woman population." (PMID 25866757, 2015). "Given that leptin levels are increased in obesity and that, due to selective leptin resistance, its proinflammatory and insulin desensitizing effects are maintained, body weight reduction is important in diabetic patients as a strategy to preserve insulin efficacy." (PMID 26578976, 2015). "Leptin is a protein synthesized in the fatty tissue and is effective in the control of obesity." (PMID 26705449, 2015).